OXT (oxytocin/neurophysin I prepropeptide)
Diseases named in the same sentence as OXT in open-access papers (continued):
Sharing a sentence is not in itself a finding about the gene and the disease.
schizophrenia (continued). "Previous research has highlighted the involvement of OXT/AVP pathways in psychotic disorders such as schizophrenia." (PMID 37373400, 2023). "Independent correlations between schizophrenia, OXT, and estrogens are evident, i.e., schizophrenia–OXT, estrogen–OXT, schizophrenia–estrogen." (PMID 36979271, 2023). "The OXT system appears to be dysregulated in the pathophysiology of schizophrenia, but the exact endogenous profile is yet to be elucidated." (PMID 36979271, 2023). "Their study focused on identifying how OXT regulates impairments in prepulse inhibition (PPI), a measure of sensorimotor gating found to be deficient in schizophrenia." (PMID 36979271, 2023). "After OXT’s natural antipsychotic properties were introduced, the relationship between the neuropeptide and positive symptoms of schizophrenia attracted significant attention." (PMID 36979271, 2023). "The aim of the present narrative review is to explore an interplay between the psychopathology of schizophrenia and the therapeutic potential of OXT, taking into consideration interactions with gonadal steroids, such as estrogens." (PMID 36979271, 2023). "OXT and AVPR1a gene expression at both the mRNA and protein levels were significantly lower in the schizophrenia group, and OXTR and AVP gene expression at both the mRNA and protein levels was higher in the schizophrenia subjects than in the controls." (PMID 35723404, 2022). "OXT and AVPR1a gene expression was significantly lower in the schizophrenia group than in the controls, whereas OXTR and AVP gene was significantly higher in the schizophrenia subjects than in the controls." (PMID 35723404, 2022). "Our data found significant H3K9me2 enrichment on the OXT promoter, correlating with significantly decreased oxytocin mRNA levels in postmortem brain tissue of individuals with schizophrenia." (PMID 36386965, 2022). "In contrast, a modest rise of plasma OXT levels in females with schizophrenia during a film’s bonding scene, but its significant decrease during an abandonment scene was reported." (PMID 32255800, 2020). "In summary, our findings corroborate a potential role of OXT in deficits of cognitive empathy in schizophrenia." (PMID 32255800, 2020). "In 35 patients with schizophrenia and 35 matched HCs, radioimmunoassay with sample extraction was used to determine OXT plasma levels before and after viewing of movie scenes portraying emotional bonding and loss and compared to a non-emotional condition." (PMID 30481342, 2019). "In contrast to schizophrenia patients, we observed decreased OXT levels after viewing emotional movie scenes in healthy women." (PMID 30481342, 2019). "Our findings suggest differences of baseline OXT and a higher OXT reactivity toward strong emotional stimuli in patients with schizophrenia, suggesting a role of OXT as a gender- and context-dependent modulator of socio-emotional function." (PMID 30481342, 2019). "This study corroborates previous evidence of an alteration of the oxytocinergic system in schizophrenia by measuring peripheral OXT at baseline and after stimulation in an attachment-related experimental setting." (PMID 30481342, 2019). "The goal of this study was to compare baseline endogenous OXT levels as well as OXT level changes induced by social stimuli between groups of schizophrenia patients and healthy controls (HCs)." (PMID 30481342, 2019). "In this study, emotional children’s movies were used to stimulate OXT secretion in patients with schizophrenia and healthy controls (HCs)." (PMID 30481342, 2019). "In schizophrenia, a morphometric evaluation of neurophysin immunoreactivity in the brain of untreated schizophrenic patients revealed an altered OXT function." (PMID 22997507, 2012). "It was shown in the early 1970s that OXT has the potential to reduce psychotic symptoms in schizophrenia." (PMID 22510359, 2012).
schizophrenia (continued). "Similarly, significantly lower OXT plasma levels have been reported in first-episode schizophrenia patients, although mRNA expression of OXT and OXTR genes were higher than in healthy controls." (PMID 36979271, 2023). "On the contrary, Jobst and colleagues reported significantly lower plasma OXT levels in schizophrenia speculating that the decrease may be due to altered OXT metabolism or a decrease in OXT synthesis and in mRNA expression and translation." (PMID 36979271, 2023). "In contrast, lower plasma OXT relates to greater asociality, poor metacognition, low facial emotion recognition accuracy, and may predict emotional and social withdrawal in schizophrenia." (PMID 36979271, 2023). "Thus, sex hormonal fluctuations during the female menstrual cycle are an essential consideration in the psychopathology of schizophrenia and in the dysregulation of the OXT system." (PMID 36979271, 2023). "Indeed, the endogenous OXT system appears to be dysregulated in the clinical course of schizophrenia, while exogenous OXT is proposed as an antipsychotic and prosocial agent." (PMID 36979271, 2023). "The discrepancy in OXT concentrations may be due to dysregulation of the endogenous OXT system in schizophrenia." (PMID 36979271, 2023). "When compared to healthy control subjects, some patients with dopamine-dependent disorders (e.g., Parkinson’s disease or schizophrenia) have abnormal peripheral (plasma) and central (cerebrospinal fluid) OXT levels as well as fewer OXT+ neurons in the hypothalamus (in post-mortem tissue)." (PMID 37445607, 2023). "Furthermore, a significant correlation of OXT gene expression at the mRNA and protein levels with the severity of depressive symptoms in schizophrenia as assessed by CDSS was found." (PMID 35723404, 2022). "In this exploratory study investigating the relationship between behavioral correlates of empathy and oxytocin (OXT) in schizophrenia, endogenous OXT level changes induced by emotional children’s movies were inversely correlated with MET cognitive empathy for negative emotional valences in patients." (PMID 32255800, 2020). "However, results from trials using intranasal OXT in patients with schizophrenia have been mixed, some reporting improvement of positive and negative symptoms or improvement of specific deficits, while others reported no benefit." (PMID 30481342, 2019). "An initial study found elevated CSF levels of OXT in patients with schizophrenia compared to healthy controls, which were higher in those patients receiving antipsychotic treatment, whereas a follow-up study could not confirm these results." (PMID 22510359, 2012). "This assumption is supported by preliminary evidence about beneficial effects of high plasma OXT levels or intranasal OXT administration on psychotic symptoms and also on theory of mind, social perception or verbal memory in schizophrenia." (PMID 23284802, 2012). "However, another study demonstrated reduced OXT serum levels in patients with schizophrenia, which additionally predicted their ability to correctly identify facial emotions." (PMID 22510359, 2012). "Therefore, the interaction between estrogen’s neuroprotective features and OXT’s antipsychotic and prosocial properties may have a synergistic therapeutic effect in schizophrenia’s psychopathology." (PMID 36979271, 2023). "Thus, and given the crucial role of DA in the pathophysiology of schizophrenia, it has been hypothesized that OXT affects symptoms of schizophrenia due to interactions between OXT and DA pathways." (PMID 32255800, 2020). "Early suggestions of OXT as a `natural antipsychotic’ and evidence from animal studies demonstrating OXT to counteract excessive mesolimbic dopamine and cortical hypoglutamatergia led to the assumption that OXT signaling might be altered in schizophrenia." (PMID 30481342, 2019).
schizophrenia (continued). "In addition, sex differences indicate that higher endogenous OXT levels correlate with greater performance in the emotional identification of body gestures in female, compared to male subjects, while female patients with schizophrenia perceive facial expressions as happier when OXT levels are high." (PMID 36979271, 2023). "The aim of this study was to evaluate the expression of OXT, OXTR, AVP, and AVPR1a genes at the mRNA and protein levels in patients with schizophrenia." (PMID 35723404, 2022). "The expression of OXT, OXTR, AVP, and AVPR1a genes at the mRNA and protein levels differ between the studied groups of patients with schizophrenia and the control group." (PMID 35723404, 2022). "The aim of this study was to evaluate the expression of OXT, OXTR, AVP, and AVPR1a genes at the mRNA and protein levels in patients who have been suffering from schizophrenia for a long or short time." (PMID 35723404, 2022). "This locus harbors four strong candidate genes for schizophrenia: attractin (ATRN), pantothenate kinase 2 (PANK2), oxytocin (OXT), and arginine–vasopressin (AVP)." (PMID 34869343, 2021). "So, in this study, we determined the relative mRNA expression of OXT and OXTR genes in first-episode, unmedicated schizophrenia (FES) patients and HC." (PMID 31024366, 2019). "In this study, we examined the relative mRNA expression of OXT, OXTR, AVP, AVPR1a and CD38 in HC and first-episode, unmedicated schizophrenia (FES) patients." (PMID 29108272, 2017). "Individuals with obsessive compulsive disorder (OCD), ASDs, eating disorders, addiction, schizophrenia, and posttraumatic stress disorder (PTSD) show dysregulation of OXT levels." (PMID 23335873, 2012). "The statistical analyses comparing the expression values of OXT, OXTR, AVP, and AVPR1a genes in the investigated groups allow us to conclude that all the examined genes may participate in the etiopathogenesis of schizophrenia." (PMID 35723404, 2022). "Moreover, the arginine vasopressin (AVP) system, which is evolutionarily related to the OXT system, shows cross-talk with the OXT system in a variety of different contexts, such as female aggression, substance use disorder, or ASD and schizophrenia." (PMID 34445168, 2021). "However, genetic data on PRLRH, PRLR, OXT, OXTR, and NPY in human T2DM and schizophrenia patients are scarce." (PMID 33315097, 2021). "In contrast, a study carried out by this work group found pronounced OXT increases in schizophrenia patients, but not in healthy controls after exposure to children’s movie scenes of attachment and loss." (PMID 32255800, 2020). "In this study, serum OXT, OXT receptor (OXTR), interleukin-6 (IL-6), high sensitivity CRP (hsCRP) and homocysteine (Hcy) levels were measured in 52 first-episode schizophrenia (FES) patients and 41 healthy controls (HC) from the Second Xiangya Hospital of Central South University." (PMID 31024366, 2019). "In trust-related interpersonal interactions, healthy controls showed increased plasma levels of OXT, whereas this effect was absent in patients with schizophrenia." (PMID 22510359, 2012). "The research results revealed a relationship between the OXT gene expression at the mRNA and protein levels with the severity of depressive symptoms that were assessed by CDSS in the group of patients who have been suffering from schizophrenia for a short time." (PMID 35723404, 2022). "Moreover, the expression of OXT, OXTR, and AVPR1a genes both at the mRNA and protein levels differed statistically significantly in the group of individuals that were suffering from schizophrenia for a long and short period." (PMID 35723404, 2022). "OXT, OXTR, AVP, and AVPR1a are genes that may be involved in the development of schizophrenia." (PMID 35723404, 2022).
schizophrenia (continued). "While some studies have highlighted a potential role of OXT in mitigating the deficits of social cognition in schizophrenia, a recent meta-analysis could not confirm a beneficial effect of OXT on negative, positive or general psychopathology." (PMID 32255800, 2020).
autism spectrum disorder (36 papers, 2009 to 2026). A spectrum of developmental disorders that includes autism, and Asperger syndrome. "Altered IC function and OXT signaling have also been implicated in neurodevelopmental disorders characterized by social deficits, including autism spectrum disorder." (PMID 41970203, 2026). "Abnormalities in either the OXT peptide or its receptor have been associated with social deficits that are prevalent in many psychiatric and neurodevelopmental disorders, including autism spectrum disorders (ASDs)." (PMID 40858267, 2025). "Finally, we discuss the genetic findings implicating several glutamatergic genes in neurodevelopmental disorders, including autism spectrum disorder, thus underscoring the need for future studies to investigate the impact of these mutations on hypothalamic glutamatergic circuits and the OXT system." (PMID 34786775, 2021). "Notably, OXT, Robo2 and Slit3 have all been implicated in Autism spectrum disorders." (PMID 31180321, 2019). "Oxytocin (OXT) is known to modulate social behavior and cognition and has been discussed as pathophysiological and therapeutic factor for autism spectrum disorder (ASD)." (PMID 38228703, 2024). "In particular, treatment with exogenous OXT has been considered in the context of autism spectrum disorder (ASD)." (PMID 36053298, 2022). "More evidence supports the potential clinical efficacy of OXT in autistic spectrum disorders (ASD) (Parker and others 2017; Yatawara and others 2016)." (PMID 32981445, 2021). "Moreover, differential OXT agonism at AVPR1a could have important implications for understanding the therapeutic potential of nonapeptide treatments in alleviating symptoms associated with neurodevelopmental disorders such as autism spectrum disorders (ASD)." (PMID 31664130, 2019). "Finally, we focus on both single nucleotide polymorphisms (SNPs) of the human CD38 gene in relation to autism spectrum disorders (ASDs) and repetitive treatment of ASD patients with nasal administration of OXT." (PMID 23335873, 2012). "The neuropeptide oxytocin (OXT) modulates social cognition by increasing attention to social cues and may have therapeutic potential for impaired social attention in conditions such as autism spectrum disorder." (PMID 36053298, 2022). "Furthermore, we speculate that investigating the impact of mutations in glutamatergic genes on these circuits, as well as on the OXT system, will be of significant relevance to neurodevelopmental disorders characterized by social behavior deficits, including autism spectrum disorder (ASD)." (PMID 34786775, 2021). "In patients with Autistic spectrum disorder (ASD), intranasal OXT has been shown to provide some improvements in adult social cognition and youth emotional recognition." (PMID 29843655, 2018). "Oxytocin (OXT) and arginine-vasopressin (AVP) play a key regulatory part in social and affiliative behaviors; two aspects highly compromised in Autism Spectrum Disorder (ASD)." (PMID 29487501, 2018).
diabetes (13 papers, 2012 to 2025). "Most notable of those was the neuropeptide Avp, which, like OXT, is expressed primarily in the SON and PVN and associated with body weight regulation and diabetes and was upregulated in the hypothalamus of the SO + CO and PL + CO diets." (PMID 31912136, 2020). "To summarize, these observations indicate that OXT and OXT analogs have potentials to improve insulin secretion to counteract glucose disorders in diabetes." (PMID 23700406, 2013). "To dissociate the possible anti-diabetic action of OXT from its weight loss-inducing effect, we used acute experimental paradigm for mouse models of HFD-induced prediabetes or STZ-induced diabetes." (PMID 23700406, 2013). "OXT levels were reduced in patients with type 1 and type 2 diabetes mellitus." (PMID 35525976, 2022). "Indeed, others have reported that both spontaneous and induced diabetes results in an increase in hypothalamic Oxt mRNA and an increase in hypothalamic OXT protein immunointensity." (PMID 31912136, 2020). "As OXT can dramatically change the energy balance, it is predictable that OXT could effectively modulate the pathogenesis of diabetes mellitus, atherosclerosis, and other metabolic diseases." (PMID 24967304, 2013). "In addition, we found that high glucose suppresses OXT expression, even though this cannot be inherited in offspring, indicating that diabetes may suppress OXT-mediated physiological processes, which is consistent with previous findings." (PMID 33633538, 2021). "However, it is unclear whether OXT stimulates GI transit, or slows it—as observed in patients with diabetes mellitus and gastroparesis after intravenous infusions." (PMID 32485966, 2020). "However, scarce information exists regarding the interaction of OXT with T lymphocytes in diabetes." (PMID 29867762, 2018). "Regarding diabetes mellitus type 2 (T2DM), OXT is involved in glucose homeostasis by increasing glycogenolysis as well as glycogenesis." (PMID 22997507, 2012). "In addition to these metabolic effects, we noted that OXT treatment tended to improve blood glucose and insulin homeostasis; under this scope, while clinical studies based on diabetic patients are needed, we employed mouse models to examine if OXT could use treat diabetes." (PMID 23700406, 2013).